TNS4 (tensin 4)
Diseases named in the same sentence as TNS4 in open-access papers (continued):
Sharing a sentence is not in itself a finding about the gene and the disease.
cancer (31 papers, 2014 to 2025). A tumor composed of atypical neoplastic, often pleomorphic cells that invade other tissues. "For example, S100P is ever reported to be involved in the aggressive properties of cancer cells and associated with poor prognosis; TNS4 is associated with cancer cell motility and migration, whose high expression can indicate poor prognosis." (PMID 37303949, 2023). "Similarly, TNS4 has been implicated in cell migration and invasion, which are key processes in cancer progression, further supporting its candidacy as a prognostic marker." (PMID 39766765, 2024). "High expression of TNS4 in tumors was shown to associate with poor survival in different cancers." (PMID 36428623, 2022). "Tensins play significant roles in cancer-related signaling pathways and exhibit regulatory functions in malignancies, with earlier studies highlighting the predominant oncogenic activities of TNS4 across diverse cancers." (PMID 40906372, 2025). "Regarding cancer metastasis, RNA-seq data of GC/lymph node tissues revealed metastatic lymph node-specific TNS4 upregulation, validated by qPCR/Western blot." (PMID 40906372, 2025). "Two genes FOLR1 and TNS4 exhibit context-dependent roles in cancer, acting as oncogenes or tumor suppressors depending on tissue type and expression levels." (PMID 41439026, 2025). "Numerous clinical studies collectively demonstrated TNS4’s predominant oncogenic functions across diverse cancers." (PMID 40906372, 2025). "In contrast, TNS4 acts predominantly as an oncoprotein across carcinomas by stabilizing epidermal growth factor receptor (EGFR), driving epithelial–mesenchymal transition and invasion, and sustaining proliferation." (PMID 40906372, 2025). "Collectively, these findings underscore the clinical importance of TNS4 as a prospective therapeutic target across a spectrum of cancers." (PMID 38164166, 2024). "The findings indicated a significant decrease in TNS4 expression in cancer cells treated with shTNS4 compared to control cells." (PMID 38164166, 2024). "MTT and EdU assays revealed notable reductions in optical density (OD) values at specified time points and a substantially lower percentage of EdU-positive cells in TNS4-depleted cancer cells." (PMID 38164166, 2024). "Our data revealed that cancer cells overexpressing TNS4 exhibited a marked increase in proliferation compared to control cells, as evidenced by MTT and EdU assays." (PMID 38164166, 2024). "The relationship between TNS4 expression and cancer patient survival was evaluated with Kaplan–Meier survival curves and meta-analyses." (PMID 36281194, 2022). "In previous studies, all four genes (ADHFE1, CNRIP1, MAFB, and TNS4) have been reported as cancer-related genes." (PMID 36158666, 2022). "Correspondingly, TNS4 plays an important role in the invasion and motility of cancer cells, including CRC." (PMID 36158666, 2022). "EGFRAP and PVRAP have been proposed to be orthologs of human TNS2 and TNS4 (FlyBase), proteins that in knockdown conditions increase tumorigenicity in several cancer lines." (PMID 34411095, 2021). "Our findings further provide a new mechanism by that TNS4 is posttranscriptionally regulated by miR-1224-5p in cancer cells." (PMID 32732965, 2020). "TNS4 plays an important part in stability of receptor tyrosine kinase, thus regulating survival and proliferation of carcinoma cells." (PMID 32188434, 2020). "Aberrant expression of TNS4 was reported in cancers of the breast, colon, pancreas, and lung, and its expression was associated with poorer prognosis of these patients." (PMID 31052206, 2019). "Clinical and mechanistic profiles of TNS4 in different cancers." (PMID 40906372, 2025). "In stark contrast, TNS4 consistently promotes migration and invasion across cancers." (PMID 40906372, 2025). "Notably, TNS4’s predominant oncogenicity across diverse cancers highlights its therapeutic targeting potential." (PMID 40906372, 2025). "Conversely, TNS4 predominantly fuels cancer advancement across carcinomas." (PMID 40906372, 2025).
cancer (continued). "The absence of N-terminal domains in TNS4 likely underlies its functional divergence toward amplified signal transduction at focal adhesions, a mechanism frequently dysregulated in cancer, which thereby drives disease progression." (PMID 40906372, 2025). "Notably, TNS4’s predominant oncogenicity across diverse cancers highlights its therapeutic targeting potential, though this requires further preclinical and clinical validation." (PMID 40906372, 2025). "TNS4 expression is downregulated in prostate tumor tissues and cancer cell lines." (PMID 40906372, 2025). "Importantly, this corroborates previous studies that have identified TNS4 overexpression in a variety of other cancers." (PMID 38164166, 2024). "However, the data also indicate the potential contribution of alternative signaling pathways to the enhancement of EMT processes and metastatic potential in cancer cells influenced by TNS4." (PMID 38164166, 2024). "Knockdown of human TNS2 and TNS4 increases tumorigenicity in several cancer lines." (PMID 37510408, 2023). "Other studies indicated that TNS4 could promote cancer progression by regulating the Akt/GSK-3b and TGF-b1 signaling pathways." (PMID 37510408, 2023). "Among these targets, aberrant expression of TNS4 enhanced cancer aggressiveness, suggesting that TNS4 could be a promising therapeutic target for LUAD." (PMID 31052206, 2019). "Notably, the absence of the N-terminal ABD and PTP-C2 in TNS4 highlights a major evolutionary divergence within the family, potentially linked to its distinct roles in cancer progression." (PMID 40906372, 2025). "Given its dual role as both an EGFR modulator and downstream effector in Ras/Raf/Mek/MAPK signaling, combinatorial targeting of TNS4 and EGFR represents a rational strategy for EGFR-dysregulated cancers." (PMID 40906372, 2025). "Mechanistic studies on HEK293T cells and cancer cell lines (SW480 colon, A549 lung, 5637 bladder) show that the TNS4 SH2 domain interacts with EGFR-phosphorylated c-Cbl, sequestering it away from activated EGFR." (PMID 40906372, 2025). "Thus, the balanced expression of TNS4 is essential for the proliferation, invasion, and development of normal cells, and its aberrant upregulation could play a pivotal role in promoting the malignant behaviors of cancer cells." (PMID 38164166, 2024). "This interaction between TNS4 and MET is direct, and TNS4 plays a role in maintaining MET stability, thereby supporting cancer cell survival." (PMID 38134011, 2023). "It has been revealed that TNS4 interacts with MET signalling, a process known to enhance motility, cancer cell survival, and angiogenesis." (PMID 38134011, 2023). "For example, upregulation of CEMIP, RRM2, LAMC2, SCD, TNS4, and PLAU in humans is prognostically unfavorable for various cancers; these genes have CR-upregulated mouse orthologs." (PMID 34202278, 2021). "As a result, overexpression of TNS4 stabilized EGFR and enhanced its oncogenic signaling in cancer cells." (PMID 31052206, 2019). "The representative genes used were ALDH3A1, TNS4, CLDN2, and ALDKETO, and are known to play important roles in cancer cell de-differentiation, migration, invasion, proliferation and apoptosis suppression." (PMID 24884630, 2014). "The expression of some genes, such as ALDH3A1, TNS4, CLDN2, and AKR1B10, which are known to play important roles in cancer cell migration, invasion, proliferation and apoptosis, were increased in HCT-8 R cells." (PMID 24884630, 2014). "Unlike TNS1/3, which anchor actin to mechanically stabilize cells, TNS4’s ABD-free structure may favor rapid signal transduction, a trait potentially advantageous for cancer cell migration." (PMID 40906372, 2025). "Nevertheless, to our knowledge, correlation of circulating TNS4 with cancer cachexia has not previously been reported." (PMID 36428623, 2022).
cancer (continued). "Furthermore, since TNS4 modulates activated EGFR levels and acts as a downstream effector in the Ras/Raf/Mek/MAPK cascade, combinatorial targeting of TNS4 and EGFR represents a theoretically viable strategy for EGFR-dysregulated cancers." (PMID 40906372, 2025). "Our observations reveal that the enhanced proliferation observed in TNS4-overexpressing HNSCC cells is entirely abrogated by Akt inhibition, although this intervention has a negligible impact on EMT markers' expression and invasive capability of these cancer cells." (PMID 38164166, 2024). "The absence of ABD shifts TNS4’s function toward signal amplification in focal adhesions, stabilizing oncogenic receptors like EGFR and promoting EMT and invasion, thus carrying out predominate oncogenic functions across carcinomas." (PMID 40906372, 2025).
tumor (31 papers, 2016 to 2026). "TNS4 expression occurred more frequently among females and was observed when necrosis in tumor was strong." (PMID 41923376, 2026). "Considering the complex mechanisms of tumor development and the multifaceted nature of malignancy, TNS4 emerges as a potential predictive marker for LUAD, though its role in disease progression requires further comprehensive assessments." (PMID 39995671, 2025). "While TNS1–3 exhibit context-dependent dual roles as tumor suppressors or oncoproteins, TNS4 predominantly functions as an oncogenic driver." (PMID 40906372, 2025). "Challenges exist, however, as TNS4 participates in both oncogenic and tumor-suppressive pathways, complicating the balance between efficacy and toxicity." (PMID 40906372, 2025). "KEGG analysis demonstrated that circadian rhythm pathway was significantly enriched on both 3 d and 7 d, genes related to disease/tumor, including Tns4 and Neu1 (upregulated), as well as Npas2 and Cry1 (downregulated), exhibited obvious changes." (PMID 39727670, 2025). "Challenges exist, as TNS4 participates in both oncogenic and tumor-suppressive pathways, complicating the balance between efficacy and toxicity." (PMID 40906372, 2025). "The xenograft tumor model further confirmed that the increases in tumor size, weight, and volume attributable to TNS4 overexpression were partially mitigated upon treatment with either shFAK or a FAK inhibitor." (PMID 38164166, 2024). "We also observed a similar trend in TNS4 expression in GSE25099 and GSE55550 datasets, where TNS4 was overexpressed in tumor tissues relative to normal tissues." (PMID 38164166, 2024). "TGFβ signaling, known for its pivotal role in EMT processes and tumor metastasis 23, 24, was found to be enriched in TNS4-high tumor tissues across multiple independent HNSCC cohorts." (PMID 38164166, 2024). "Our findings indicated that TNS4 expression was significantly elevated in tumor tissues compared to adjacent normal tissues (ANTs) across multiple independent HNSCC cohorts, including in-house HNSCC, TCGA HNSCC, GSE37991, GSE58911, and GSE83519." (PMID 38164166, 2024). "To substantiate these findings in vivo, we utilized a xenograft tumor model and observed that TNS4-overexpressing SCC-1 cells generated tumors with considerably larger size, weight, and volume compared to tumors generated by their control counterparts." (PMID 38164166, 2024). "Colony and tumor sphere formation assays further revealed significantly reduced colony and tumor sphere formation capabilities in HNSCC cells upon TNS4 depletion compared to control cells." (PMID 38164166, 2024). "As expected, we also detected lower protein levels of EGFR and TNS4 in tumor tissues of SMARCA4-R1157W mutant CDX models after treatment with GSK-PTi and BBAi-1 by western blot and IHC analysis than those in SMARCA4-WT CDX models." (PMID 36922568, 2023). "Together, our data suggest that miR-1224-5p downregulation is a frequent alteration in ESCC that promotes cell proliferation, migration, invasion and tumour growth by activating the EGFR-EFNA1/EPHA2-VEGFA signalling pathway via inhibition of TNS4 expression." (PMID 32732965, 2020). "Database analyses (UALCAN/GEPIA) reveal significant TNS4 mRNA upregulation in tumor tissues, a finding corroborated by an immunohistochemical assessment of 92 paired paraffin blocks showing elevated protein expression, particularly in late-stage (III-IV) versus early-stage (I-II) disease." (PMID 40906372, 2025). "Furthermore, immunohistochemical analysis of 272 invasive breast carcinomas revealed elevated TNS4 protein expression correlating with a high tumor grade and lymph node metastasis, a finding confirmed in a larger tissue microarray study (n = 1409)." (PMID 40906372, 2025). "Moreover, TNS4 expression demonstrated a progressive increase from normal tissues to dysplastic tissues and ultimately to tumor tissues." (PMID 38164166, 2024).
tumor (continued). "We identified 9 genes whose increased expression was significantly associated with tumor size in female LC patients of which four code for MAPK signaling molecules (DUSP4, FGL1, TXNRD1, PLA2G4E), three for oncogenes (KRT16, STRIP2 and TNS4), tumor suppressor cystatin 5, and NQO1." (PMID 38245882, 2024). "Furthermore, the intensity of Ki-67 staining was notably elevated in xenograft tumor tissues derived from TNS4-overexpressing cells relative to those derived from control cells." (PMID 38164166, 2024). "Furthermore, matrigel invasion assay and tumor sphere-forming assay both revealed that the Akt inhibitor did indeed attenuate the enhanced invasion capacity and sphere-forming ability induced by TNS4 overexpression in HNSCC cells." (PMID 38164166, 2024). "In the context of HNSCC, characterized by hypoxia due to rapid tumor growth and impaired blood flow, this upregulation of TNS4 in hypoxic microenvironments could explain its commonly observed overexpression in tumor tissues across different cohorts." (PMID 38164166, 2024). "Subsequently, we sought to ascertain whether FAK inactivation would mitigate the tumor-promoting effects of the TNS4-integrin α5β1 axis in HNSCC cells." (PMID 38164166, 2024). "Moreover, IHC analysis showed that the staining intensity of Ki-67 was markedly lower in xenograft tumor tissues derived from TNS4-depleted cells than in those originating from control cells." (PMID 38164166, 2024). "Additionally, utilizing the 4-NQO carcinogenesis model, we observed a stepwise elevation in TNS4 expression, transitioning from normal tissues to dysplastic tissues and culminating in tumor tissues." (PMID 38164166, 2024). "miR-1224-5p inhibits tumor progression by targeting the TNS4/EGFR axis." (PMID 34778021, 2021). "The findings also indicate that miR-1224-5p inhibits cell proliferation, colony formation, migration and invasion in vitro and tumour growth in vivo by targeting TNS4, and subsequently promoting the autophagic degradation of EGFR, and suppressing downstream EFNA1/EPHA2 and VEGFA signalling pathways." (PMID 32732965, 2020). "Importantly, silencing TNS4 mitigated the effects of miR-1224-5p loss on EGFR upregulation and signaling activation, as well as inhibiting in vitro proliferation, colony formation, migration, invasion, and in vivo tumor growth." (PMID 40906372, 2025). "Among them, the epithelial cell differentiation-related KRT gene family, the cell cycle regulation gene FAM83H, and the tumor metastasis-related genes EPS8L1 and TNS4 were upregulated in metastatic TDLNs." (PMID 39753715, 2025). "Functionally, TNS4 inhibits proliferation, migration, and angiogenesis in MCF7 cells and suppresses tumor growth in nude mice by targeting VEGFA through c-Cbl-mediated β-catenin downregulation." (PMID 40906372, 2025). "The invasive and tumor sphere-forming abilities of HNSCC cells, enhanced by TNS4 overexpression, were significantly attenuated upon treatment with the TGFβ signaling inhibitor LY2109761." (PMID 38164166, 2024). "Our data reveal that the inhibition of FAK significantly curtails the tumor-promoting effects of TNS4 overexpression, underscoring the centrality of FAK activation by the integrin α5β1 complex in TNS4-mediated signaling." (PMID 38164166, 2024). "We further showed that the SMARCA4R1157W mutant reinforced the transcriptional expression of EGFR and TNS4 to promote the proliferation of CRC cells and patient-derived tumor organoids." (PMID 36922568, 2023). "Increased TNS4 expression in LUAD was closely correlated with a higher disease stage (P = .007), positive lymph nodes (P = .005), and larger tumor size (P = .002)." (PMID 36281194, 2022). "The overexpression of several target genes and pathways, such as Liver Kinase B1 (LKB1), HMGA2, Wnt-β-catenin signaling pathway, and tensin 4 (TNS4) has been attributed to the downregulation of miR-150 and can lead to NSCLC tumor progression and metastasis." (PMID 36613642, 2022).
tumor (continued). "Positive expression of TNS4 and VEGFA was detected in 6.7% and 5.2% (n = 134) of adjacent non-malignant tissues, respectively, and the positive rates of TNS4 and VEGFA in tumour tissues were 50.7% and 32.1% (n = 134), respectively." (PMID 32732965, 2020). "Our recent studies demonstrated that some passenger strands of miRNAs, e.g., miR-143-5p, miR-145-3p and miR-150-3p, behave as tumor-suppressive miRNAs in LUAD cells by targeting oncogenes, e.g., LMNB2, MCM4 and TNS4, respectively." (PMID 32932948, 2020). "Importantly, TNS4 expression in LUAD did not vary significantly across different tumor stages, indicating that its high expression in tumor tissues is not stage-dependent." (PMID 39995671, 2025). "In addition, TNS4 could inhibit the degradation of EGFR, a molecule related to tumor cell proliferation and apoptosis inhibition, through post-translational modification, and prolonged its function." (PMID 37328854, 2023). "The level of TNS4 expression in all tumor tissues was higher than that in normal tissues." (PMID 36281194, 2022). "Immunohistochemical staining conducted at Jiangmen Central Hospital confirmed higher TNS4 protein levels in LUAD than in normal lung tissue, though there was no statistical difference in expression across different tumor stages." (PMID 39995671, 2025).
infection (2 papers, 2019 to 2025). The state of being infected such as from the introduction of a foreign agent such as serum, vaccine, antigenic substance or organism. "Moreover, on 3 d and 7 d post-infection, DEGs related to gut diseases were significantly affected, particularly Ceacam10, Tns4, Neu1, Serpina10, and Npas2." (PMID 39727670, 2025).
colorectal (1 paper, 2022). "Just like MAFB, no previous studies have investigated the roles of aberrant methylation of TNS4 in colorectal carcinogenesis." (PMID 36158666, 2022).
TNS4 also shares sentences with these, for which no sentence is quoted: inflammatory breast carcinoma (2 papers); melanoma (2); thymoma (2); acute myeloid leukemia (1); adenocarcinoma (1); adenocarcinoma of the esophagogastric junction (1); benign prostatic hyperplasia (1); breast tumors (1); cholangiocarcinoma (1); colorectal tumors (1); gastrointestinal tumors (1); head and neck cancer (1); head and neck tumors (1); keratoconus (1); lentivirus infection (1); Lung Squamous Cell Carcinoma (1); neuroblastoma (1); non-small cell lung carcinoma (1); pancreatic ductal adenocarcinoma (1); prostate tumor (1); rectum adenocarcinoma (1); seborrheic keratosis (1); squamous cell carcinoma (1); stomach adenocarcinoma (1); stomach cancer (1).